XPO1 (exportin 1)
Diseases named in the same sentence as XPO1 in open-access papers (continued):
Sharing a sentence is not in itself a finding about the gene and the disease.
prostate tumor (2 papers, 2015 to 2017). "Nuclear and cytoplasmic expression of XPO-1 is elevated in prostate tumors when compared to normal and hyperplastic tissue." (PMID 29340049, 2017). "Here, we demonstrate that nuclear and cytoplasmic expression of XPO-1 is elevated in prostate tumors compared to normal and hyperplastic tissue." (PMID 26620414, 2015).
renal carcinoma (2 papers, 2014 to 2025). A carcinoma arising from the epithelium of the renal parenchyma or the renal pelvis. "Furthermore, we identified XPO1 as a potential diagnostic and therapeutic target for ccRCC, as it was found to be involved in the activation of PI3K-AKT-mTOR and interferon-alpha pathways, thereby promoting renal cancer progression." (PMID 39882192, 2025). "XPO1 is abnormally expressed in KIRC and can promote renal cancer progression through the cell cycle, interferon, and TGF-beta-related pathways." (PMID 39882192, 2025).
T-cell leukemia (2 papers, 2022 to 2024). A malignant disease of the T-lymphocytes in the bone marrow, thymus, and/or blood.
T-cell lymphoma (2 papers, 2015 to 2024). "Recently, Neggers and colleagues reported that the sensitivity of T-cell lymphoma to SINE compounds was reduced by more than 250-fold by a knock-in experiment when cysteine 528, the residue that binds SINE compounds, as well as LMB, was mutated to serine on XPO1." (PMID 26573568, 2015).
tauopathies (2 papers, 2021). "Tau‐induced nuclear envelope invaginations sequester XPO1 in a Drosophila model of tauopathy." (PMID 34019093, 2021).
thymic carcinoma (2 papers, 2023 to 2024). Thymic carcinoma (TC) is a type of thymic epithelial neoplasm characterized by a high malignant potential. "IHC analysis of 132 TET tumors and 16 normal thymic tissues revealed an association between a higher expression of XPO1 and more aggressive histologic subtypes (e.g., B2/B3 thymoma and thymic carcinoma) and advanced stages of disease." (PMID 38254905, 2024).
thymoma (2 papers, 2022 to 2024). A neoplasm arising from the epithelial cells of the thymus. "Previous nuclear and cytoplasmic mass-spectrometry proteomic profiling of XPO1 protein cargos in thymoma cell lines yielded clues into what proteins were directly affected by XPO1 blockade." (PMID 36289662, 2022).
Anorexia (1 paper, 2018). Lack of desire to eat (loss of appetite). "Dose limiting toxicities previously observed with administration of KPT-330, including weight loss and anorexia, were not seen in this study, supporting further evaluation of standard chemotherapy combined XPO1 inhibitors such as KPT-335." (PMID 30143046, 2018).
Apert syndrome (1 paper, 2023). Apert syndrome (AS) is a frequent form of acrocephalosyndactyly, a group of inherited congenital malformation disorders, characterized by craniosynostosis, midface hypoplasia, and finger and toe anomalies and/or syndactyly. "We thus tested U0126, a specific MEK1/2 inhibitor that was also previously reported in the treatment of craniosynostosis in an Apert syndrome mouse model and KPT-330, a nonreversible selective inhibitor of the nuclear exportin XPO1/CRM1 that is being tested as a potential antitumor drug." (PMID 37175668, 2023).
autism (1 paper, 2023). Persistent deficits in social interaction and communication and interaction as well as a markedly restricted repertoire of activity and interest as well as repetitive patterns of behavior. "XPO1, which is a nuclear export protein, induced apoptosis of cortical neural progenitors in mice and intronic mutations within XPO1 were associated with autism." (PMID 37254169, 2023).
bladder (1 paper, 2018). "In silico, in vitro and in vivo studies reported here show that XPO1 is expressed in most bladder malignancies, and that selinexor effectively reduces XPO1 expression and cell viability in a dose dependent manner in all cells." (PMID 30349650, 2018).
Cerebral ischemia (1 paper, 2018). Restriction of arterial blood supply to the brain associated with insufficient oxygenation to support the metabolic requirements of the tissue. "Thus, inhibition of XPO1 may prove useful in reducing neurodegeneration in these neurological disorders, including cerebral ischemia." (PMID 30497386, 2018).
childhood cancer (1 paper, 2021). "Targeting of NXT1, like XPO1, promotes cell lethality and reinforces the importance of additional research focused on nuclear export machinery in childhood cancer." (PMID 34944778, 2021). "However, XPO1 biology and selinexor sensitivity in childhood cancer is only recently being explored." (PMID 34944778, 2021). "Recent advances in the understanding of adult malignancies have demonstrated the relevance of Exportin-1 (XPO1) overexpression in highly aggressive cancers and the potential for precise therapeutic targeting, yet the overall understanding of this protein in childhood cancer is less well established." (PMID 34944778, 2021). "Our review of the current knowledge about XPO1 and XPO1 inhibition in childhood cancer offers an enthusiastic outlook about the potential for integrating XPO1-directed therapy as part of combination treatment to improve outcomes for children with highly aggressive malignancies." (PMID 34944778, 2021).
Cholecystitis (1 paper, 2022). The presence of inflammatory changes in the gallbladder. "XPO1 was barely detectable in most of cholecystitis specimens compared with cancer samples calculated by Student's t test." (PMID 36180918, 2022). "We also assessed XPO1 protein expression in 94 tissue samples of GBC and 69 cases of cholecystitis that were established as control by IHC." (PMID 36180918, 2022).
chordoma (1 paper, 2022). Chordomas are rare malignant tumors arising from embryonic remnants of the notochord in axial skeleton. "This is consistent with SINE-compound mediated XPO1 inhibition exhibiting anti-cancer activity through a broad range of different mechanisms in different molecular chordoma subsets." (PMID 36059685, 2022). "In this study, the XPO1 inhibitors, selinexor and eltanexor, were investigated as anti-cancer agents in five different chordoma patient-derived xenograft (PDX) models, as single agents or in combinations with bortezomib or abemaciclib." (PMID 36059685, 2022).
colon adenocarcinoma (1 paper, 2025). "The Gene Expression Profiling Interactive Analysis data show that XPO1 gene expression was elevated in colon adenocarcinoma tissue compared with normal colon tissue." (PMID 40601866, 2025).
cortical dysplasia (1 paper, 2023). "Deletions affecting only the BCL11A gene are not penetrant for hearing loss and IUGR traits, while those uniquely involving the USP34 and XPO1 genes are neither penetrant for cortical dysplasia nor for cerebellar anomalies." (PMID 36807877, 2023).
cyst (1 paper, 2020). A sac-like closed membranous structure that may be empty or contain fluid or amorphous material. "Treatment with a range of doses of Triptolide, Quisinostat, and the XPO1/CRM inhibitors KPT-335, KPT-330 and Leptomycin B, reduced the cyst size and cell viability compared to DMSO." (PMID 32144367, 2020).
diffuse malignant peritoneal mesothelioma (1 paper, 2015). "Survivin, which is highly expressed and promotes cell survival in diffuse malignant peritoneal mesothelioma (DMPM), exclusively relies on exportin 1 (XPO1/CRM1) to be shuttled into the cytoplasm and perform its anti-apoptotic function." (PMID 25948791, 2015).
ductal breast carcinoma (1 paper, 2021). "The Cancer Genome Atlas (TCGA) data for ductal breast carcinoma was used to evaluate XPO1 expression across different normal and cancerous breast sample groups." (PMID 34628286, 2021).
follicular lymphoma (1 paper, 2022). Follicular lymphoma is a form of non-Hodgkin lymphoma characterized by a proliferation of B cells whose nodular structure of follicular architecture is preserved. "In addition, each contingent showed its own pathogenic variants, such as BCL2, KMT2D, EP300 in the follicular lymphoma contingent, and XPO1, TNFAIP3, and CREBBP in the cHL contingent." (PMID 36428786, 2022).
H1N1 influenza (1 paper, 2023). "Research with another XPO1 inhibitor, verdinexor, against syncytial respiratory virus and H1N1 influenza (swine flu) found similar results, including decreased cytokine production and viral titer analysis." (PMID 37954586, 2023).
HCMV infection (1 paper, 2021). "While many cellular proteins utilize XPO1, of particular interest to HCMV infection is IRF3, which relies solely on XPO1 for its nuclear export." (PMID 34012430, 2021). "During the course of HCMV infection (0∼96 hpi), the degradation of XPO1 was observed after 6 h post treatment with Eltanexor, but not in vehicle (DMSO)-treated control cells." (PMID 34012430, 2021).
immune deficiency (1 paper, 2025). "Similarly, a study that measured XPO1 expression in DLBCL patient samples with different levels of immune infiltrates noted that immune deficiency was associated with high XPO1 expression." (PMID 40291981, 2025).
Intellectual disability (1 paper, 2021). "Haploinsufficiency of USP34 and XPO1 has been postulated as a mechanism of disease in a patient with mild intellectual disability and cranio-facial dysmorphisms." (PMID 34321086, 2021).
kidney infection (1 paper, 2023). "In the current study, xpo1 was identified as a core gene due to its high connectivity and interaction with six key genes in modules related to gill and kidney infection." (PMID 37570350, 2023).
lung squamous cell carcinoma (1 paper, 2019). "Accordingly, mRNAs of XPO1 and NMD3 are high in lung squamous cell carcinoma." (PMID 31113936, 2019).
lymph node metastasis (1 paper, 2022). "High level of XPO1 was closely associated with pathologic T stage (P < 0.001), lymph node metastasis (P = 0.047), and TNM stage (P = 0.001) evaluated by Pearson’s χ2 test." (PMID 36180918, 2022).
malaise (1 paper, 2014). A feeling of general discomfort or uneasiness, an out-of-sorts feeling. "As previously discussed, the primary barriers to clinical development of previous XPO1 small molecule inhibitors have consisted of marked anorexia and malaise observed in both mice and humans." (PMID 24503695, 2014).
mental disorder (1 paper, 2016). A disease that has its basis in the disruption of mental process. "More than 80 proteins were identified in neuron projection term, and these proteins may influence metabolic process or cellular process in mental disorders, such as STIL (SCL/TAL1 interrupting locus) and XPO1 (exportin 1)." (PMID 27917343, 2016).
metastatic melanoma (1 paper, 2014). A melanoma that has spread from its primary site to another anatomic site. "XPO1 protein was also consistently expressed in a panel of five human metastatic melanoma cell lines, and in three primary human melanocyte cell lines." (PMID 25057921, 2014). "A panel of human metastatic melanoma cell lines were treated with varying concentrations of the KPT-185 XPO1 inhibitor (Range = 0–10.24 μM) or DMSO (vehicle) as a negative control." (PMID 25057921, 2014). "In the present report, we demonstrate that elevated levels of XPO1 protein are present in primary as well as metastatic melanoma as compared to nevi." (PMID 25057921, 2014). "In the present study, we demonstrated that XPO1 expression was elevated in patient primary and metastatic melanomas as compared to nevi." (PMID 25057921, 2014). "Data from our study are consistent with these observations and indicate XPO1 inhibition could effectively inhibit growth, by arresting cells in G1, and inducing apoptosis within a panel of human metastatic melanoma cell lines." (PMID 25057921, 2014).
microcephaly (1 paper, 2023). A congenital or acquired developmental disorder in which the circumference of the head is smaller than normal for the person's age and sex. "Our results delineate an intricate pattern of genotype − phenotype correlation where BCL11A emerges as the main gene for autistic behavior while USP34 and/or XPO1 haploinsufficiency are mainly associated with microcephaly, hearing loss and IUGR." (PMID 36807877, 2023). "In agreement with previous reports, our investigation showed that BCL11A is particularly involved in cortical and cerebellar anomalies, and autistic behavior whereas USP34/XPO1 deletions are more associated with corpus callosum anomalies, microcephaly, IUGR, and hearing loss." (PMID 36807877, 2023). "Penetrant deletions for microcephaly outlined two SROs; SRO1 (p: 0.25, 2/8) including the BCL11A (cp: 0.23) and PAPOLG (cp: 0.13) genes, and SRO2 (p: 0.55, 6/11) overlapping the USP34 (cp: 0.77) and XPO1 (cp: 0.18) genes." (PMID 36807877, 2023).
myeloid neoplasm (1 paper, 2026). Proliferation of myeloid cells originating from a primitive stem cell. "Selective XPO1 inhibitors (selinexor, eltanexor) show preferential activity in NPM1-mutated, DEK::NUP214-positive and SF3B1-mutated myeloid neoplasms." (PMID 42071259, 2026).
Neurodevelopmental delay (1 paper, 2023). "However, our probabilistic analysis greatly favors XPO1 over USP34 as candidate gene, at least for neurodevelopmental delay." (PMID 36807877, 2023).
Opportunistic infection (1 paper, 2021). An infection that is caused by a pathogen that would generally not be able to cause an infection in a host with a normal immune system. "The role for complications stemming from E571 XPO1 mutations in modulating the immune system of CLL patients, or increasing susceptibility to opportunistic infections, remain unresolved." (PMID 33451349, 2021).
oral squamous cell carcinoma (1 paper, 2024). "However, the role of XPO1 in oral squamous cell carcinoma (OSCC) has yet to be determined." (PMID 39177040, 2024).
plasmacytoma (1 paper, 2022). Plasmacytoma is a localized mass of neoplastic monoclonal plasma cells that represents approximately 5% of all plasma cell neoplasms. "Unfortunately, daratumumab and the XPO-1 inhibitor selinexor have shown limited efficacy in patients with advanced disease and plasmacytomas." (PMID 36114167, 2022).
prostate adenocarcinoma (1 paper, 2025).
pulmonary fibrosis (1 paper, 2025). Chronic progressive interstitial lung disorder characterized by the replacement of the lung tissue by connective tissue, leading to progressive dyspnea, respiratory failure, or right heart failure. "The Exportin 1 (XPO1) inhibitor Selinexor similarly targets GBP5 to suppress the NLRP3 pathway, alleviating pulmonary fibrosis." (PMID 40788157, 2025).
rhabdoid tumor (1 paper, 2021). An aggressive malignant embryonal neoplasm usually occurring during childhood. "Selinexor, a selective exportin-1 inhibitor, was effective in inhibiting the nuclear export of SMARCB1(Q318X) and caused rapid cell death in rhabdoid tumor cells." (PMID 34003336, 2021).
synucleinopathies (1 paper, 2021). "Of note, Lewy body formation related to synucleinopathies has been associated with altered KPNA7 and XPO1/exportin-1 expression, while inhibition of KPNA2 impaired the pathological accumulation of α-syn in the nucleus." (PMID 34019093, 2021).
thyroid cancer (1 paper, 2019). "In the context of thyroid cancer, studies have shown that XPO1 and related exportins influence thyroid hormone receptor nuclear export and function." (PMID 31905765, 2019).
Wilms tumor (1 paper, 2024). An embryonal neoplasm characterized by the presence of epithelial, mesenchymal, and blastema components. "From 12,719 patient samples, we found 85.4% of Wilms Tumor samples were in the top 20% of samples with high XPO1 levels." (PMID 38589567, 2024).
cancer (285 papers, 2006 to 2025). A tumor composed of atypical neoplastic, often pleomorphic cells that invade other tissues. "XPO1 overexpression is associated with cancer progression, treatment resistance, and inferior overall or progression-free survival." (PMID 41279557, 2025). "Recurrent codon E571 mutations within the XPO1 cargo binding groove have been reported in multiple cancer types but most frequently occur in B-cell malignancies." (PMID 40291981, 2025). "Inhibition of XPO1 reduces the nuclear export of these factors, attenuating pro-tumorigenic signaling and enhancing the susceptibility of cancer cells to immune-mediated clearance and chemotherapy." (PMID 41440011, 2025). "Exportin 1 inhibitors disrupt the translocation and restore their function to inhibit cancer growth, stop the cell cycle, and cause cell death." (PMID 40872651, 2025). "In cancers, the mislocalization of many tumor-suppressing proteins (TSPs) caused by the overexpression of the nuclear export protein XPO1 contributed to cell proliferation and increased metastatic potential." (PMID 40872651, 2025). "Overexpression of XPO1 has been observed in various cancers, including ccRCC, and has been associated with poor prognosis and drug resistance." (PMID 39882192, 2025). "The present study demonstrated that mutations in the XPO1 gene result in alterations at the molecular level in cancer cells, particularly in lymphoid malignancies." (PMID 40806458, 2025). "As XPO1 has broad functions in physiology and cancer, it was implicated as a general target in many cancers, including AML." (PMID 40148556, 2025). "Although there have been no reports on the impact of their mutations and amplifications and mutations on outcomes in NSCLC, XPO1 has been shown to be involved in the development of other cancer types." (PMID 38820302, 2024). "In particular, the SINE inhibitors cause a reduction in XPO1 protein levels via the proteasomal pathway, offering a potential therapeutic benefit in various diseases, especially cancer." (PMID 38892287, 2024). "Exportin 1 (XPO1) is a transporter protein whose upregulation leads to the inactivation of tumor suppressors and loss of anti-tumor function in many cancers, making it a validated drug target." (PMID 39464634, 2024). "In summary, we found that XPO1+Epithelial constitute a cluster of cells characterized by TP high-risk subtypes, which exhibit elevated expression in cancer tissues." (PMID 39712016, 2024). "A subsequent study revealed that tumour cells induced GPER nuclear export via an XPO1‐dependent pathway in cancer‐associated fibroblasts by activating the PI3K/AKT signalling pathway." (PMID 38783482, 2024). "The overexpression of XPO1 has been identified in various cancers, including MDS, and is associated with a poor prognosis." (PMID 38997434, 2024). "We now describe a molecular mechanism underlying a KIR2DS2 specific response against cancer and identify that, in multiple cancers, the combination of XPO1 and NK cells are associated with longer survival." (PMID 39178254, 2024). "XPO1 overexpression has been shown to be a hallmark of a number of cancers, including multiple solid tumours." (PMID 37601856, 2023). "First, the subinteractomes of these ORF proteins contain proteins associated with ‘cancer hallmark’ and oncoproteins (e.g., the case of C5orf24 and its protein partners XPO1, PBX1, MYC, CIC, GOPC, CREB1 and STK11)." (PMID 37373333, 2023). "XPO1 inhibition has also been shown to inhibit neutrophil extracellular trap formation, which has been associated with cancer progression." (PMID 37601856, 2023). "Selinexor is a novel, first-in-class oral selective inhibitor of nuclear export (SINE) compound that blocks XPO1, forcing the nuclear retention and activation of TSPs, ultimately causing cancer cell death." (PMID 34802051, 2022).